FBLN7 (fibulin 7)
Description:
An adhesion molecule that interacts with extracellular matrix molecules in developing teeth and may play important roles in differentiation and maintenance of odontoblasts as well as in dentin formation.
Synonyms: TM14; FLJ37440
Tractability: Antibody: UniProt places it where antibodies can reach, with medium confidence; UniProt predicts a signal peptide or a membrane-spanning region; its Gene Ontology location is reachable by antibodies, with medium confidence; the Human Protein Atlas places it where antibodies can reach.
Gene: Protein-coding gene on chromosome 2 (112,138,385 to 112,188,218, forward strand). Ensembl gene ENSG00000144152.
Subcellular location: Secreted, extracellular space, extracellular matrix
Subcellular location (Human Protein Atlas): Plasma membrane; Cell Junctions; Predicted to be secreted
Gene Ontology:
Molecular function: calcium ion binding; heparan sulfate proteoglycan binding; heparin binding
Cellular component: focal adhesion; elastic fiber; extracellular matrix; non-collagenous component of interstitial matrix; extracellular region
Genetic constraint (gnomAD): Loss-of-function variants: 31 observed, 40.47 expected, observed/expected ratio (o/e) 0.77, 90% interval 0.57 to 1.03. The upper end of that interval is the gene's LOEUF score, 1.03, which puts it in group 4 of 6, group 1 being the genes least tolerant of losing a copy. Missense variants: 573 observed, 602.14 expected, observed/expected ratio (o/e) 0.95, 90% interval 0.89 to 1.02. Synonymous variants: 262 observed, 245.7 expected, observed/expected ratio (o/e) 1.07, 90% interval 0.96 to 1.18.
Homologues: Orthologues: chimpanzee FBLN7 (98% identical), macaque TMEM87B (97% identical), pig FBLN7 (91% identical), dog FBLN7 (89% identical), guinea pig FBLN7 (87% identical), mouse Fbln7 (85% identical), rat Fbln7 (85% identical), rabbit FBLN7 (80% identical), tropical clawed frog fbln7 (69% identical), zebrafish fbln7 (63% identical), Caenorhabditis elegans T25C12.3 (18% identical), Caenorhabditis elegans ZK1193.2 (18% identical), and 6 more. Paralogues in human: CD93 (22% identical), DLL3 (19% identical), CRELD1 (18% identical), DLK2 (18% identical), CRELD2 (16% identical), CD248 (15% identical), WIF1 (14% identical), CLEC14A (9% identical).
Diseases named in the same sentence as FBLN7 in open-access papers:
FBLN7 is named in the same sentence as 42 diseases in open-access papers, as found by Europe PMC text mining. Sharing a sentence is not in itself a finding about the gene and the disease. The quoted sentences say what the papers report.
glioblastoma (5 papers, 2020 to 2023). The most malignant astrocytic tumor (WHO grade IV). "A recent study implicated fibulin 7 (Fbln7)—highly expressed in endothelial cells and pericytes—in the formation of these vascular structures in glioblastoma." (PMID 33921099, 2021). "TdTOSX single positive cells also expressed high levels of fibulin 7 (Fbln7), a cell adhesion molecule overexpressed in glioblastoma by pericytes and involved in neovascularization." (PMID 32755539, 2020). "Moreover, very recently, overexpression of Fbln7 has also been observed in certain cancers such as glioblastoma." (PMID 32429873, 2020). "In fact, the matricellular protein fibulin-7, which is crucial for the formation of aberrant blood vessels in GBM, was overexpressed in the glioblastoma microenvironment, particularly in perivascular cells such as pericytes." (PMID 37174724, 2023). "Interestingly, in contrast to the C-terminal fragments of Fbln7, the N-terminal fragment was shown to interact with Ang1 and suppress Tie2 activation in endothelial cells, ultimately resulting in aberrant blood vessel formation, which is a characteristic pathology in glioblastoma." (PMID 32429873, 2020).
Myocardial fibrosis (3 papers, 2023 to 2025). "Our results demonstrated the cardioprotective effects of FBLN7 KO in aged mice, which reduces age-related myocardial fibrosis and ultimately enhances cardiac diastolic function." (PMID 40860136, 2025). "We have previously demonstrated that FBLN7 promotes myocardial fibrosis through the activation of CFs under pathological conditions." (PMID 40860136, 2025). "The observation that overexpressing FBLN7 in FSP1+ cells of aged mice exacerbates age-related myocardial fibrosis reinforces this finding." (PMID 40860136, 2025). "The observation that overexpressing FBLN7 in fibroblast-specific protein 1 positive (FSP1+) cells of aged mice exacerbates age-related myocardial fibrosis further supports this finding." (PMID 40860136, 2025). "Recent research suggested that FBLN7 is involved in the pathogenesis of myocardial infarction, with FBLN7 knockout mice exhibiting reduced myocardial fibrosis post-infarction." (PMID 39659565, 2024). "Taken together, FBLN7 overexpression aggravated myocardial fibrosis and cardiac dysfunction after MI." (PMID 37344348, 2023). "Excessive deposition of collagen I and III and myocardial fibrosis were also observed in the infarct and border areas of Fbln7+/+ hearts after MI." (PMID 37344348, 2023). "Masson and Sirius red staining showed that FBLN7 overexpression aggravated myocardial fibrosis and collagen deposition in the border and remote areas of the infarcted hearts compared to the control group." (PMID 37344348, 2023). "The authors demonstrate that FBLN7 deletion attenuated post‐MI cardiac remodeling, leading to better cardiac function and reduced myocardial fibrosis, whereas overexpression of FBLN7 results in the opposite effects." (PMID 37344348, 2023). "We hope that this study will contribute to a deeper understanding of the pathogenesis of myocardial fibrosis and fill the gap in our understanding of FBLN7." (PMID 37344348, 2023). "Therefore, it is reasonable to conclude that FBLN7, as a pro-fibrotic factor in myocardial fibrosis, is elevated in aging hearts and diminished in impaired profibrotic senescent CFs." (PMID 40860136, 2025). "Furthermore, we demonstrated that GRO intervention inhibited the profibrotic phenotypes promoted by FBLN7 overexpression in aging CFs, as well as diastolic dysfunction and myocardial fibrosis in aging mice." (PMID 40860136, 2025). "Taking all factors into account, our results demonstrate that FBLN7 is a key regulator of myocardial fibrosis in the context of aging and reveals its potential to reverse the impaired profibrotic phenotypes of senescent CFs, which may contribute to the pathogenesis of age-related cardiac fibrosis." (PMID 40860136, 2025). "Therefore, GRO may also improve age-related myocardial fibrosis by reducing the level of FBLN7." (PMID 40860136, 2025). "However, the function of FBLN7 in myocardial fibrosis within the context of aging remains unclear." (PMID 40860136, 2025).
cardiac hypertrophy (2 papers, 2023 to 2025). "The protective effects of FBLN7 KO in ageing hearts may associated with increasing myocardial glycogen and/or improving 'energy reserve', as the impaired myocardial energetics occurs in cardiac hypertrophy." (PMID 40860136, 2025). "Furthermore, hematoxylin and eosin (HE) and wheat germ agglutinin (WGA) staining of heart sections demonstrated reduced cardiac hypertrophy and a decrease in cardiomyocyte cross-sectional area after FBLN7 deletion." (PMID 40860136, 2025).
congenital heart defects (2 papers, 2018 to 2023). "FBLN7 and TMEM87B in 2q13 locus could confer susceptibility to congenital heart defects." (PMID 36816019, 2023).
fibrosis (2 papers, 2023 to 2025). the formation of excess fibrous connective tissue in an organ or tissue in a reparative or reactive process. "Notably, we found that the deletion of FBLN7 alleviates age-related fibrosis possibly by promoting CF senescence." (PMID 40860136, 2025).
abdominal aortic aneurysm (1 paper, 2024). Enlargement and ballooning of the vessel that supplies arterial blood to the abdomen, pelvis and legs. "To preliminarily investigate whether FBLN7 is involved in vascular remodeling, we analyzed high-throughput sequencing data from two typical vascular remodeling models, abdominal aortic aneurysm (AAA) and hypertensive vascular remodeling, in the GEO database." (PMID 39659565, 2024).
age (1 paper, 2025). A temporal measurement of the time period elapsed since an identifiable point in the life cycle of an organism. "In our study, we aim to explore whether FBLN7 is also involved in the development of age-related cardiac fibrosis and its underlying mechanisms." (PMID 40860136, 2025). "Collectively, the protective function of FBLN7 deletion in age-related cardiac fibrosis and diastolic dysfunction may be attributed to the loss of its profibrotic and anti-senescent effects on CFs." (PMID 40860136, 2025).
age-related macular degeneration (1 paper, 2017). Age-related loss of vision in the central portion of the retina (macula), secondary to retinal degeneration. "The gene fibulin 7 (Fbln7), important for extracellular matrix adhesion and cytoskeletal rearrangement, has a SNP associated with age-related macular degeneration and its expression is altered in patients with retinoschisis, a form of inherited retinal dystrophy." (PMID 29116131, 2017).
bleeding disorder (1 paper, 2020). "One of these loci encompasses an important ECM-related gene, FBLN7 that is associated with antepartum haemorrhage (APH), a bleeding disorder that manifests from week 24 until childbirth." (PMID 32403311, 2020).
cataract (1 paper, 2017). Partial or complete opacity of the crystalline lens of one or both eyes that decreases visual acuity and eventually results in blindness. "The prenatal, postnatal (1–60 h), and cataract mouse signals were detected at the specific band of FBLN7." (PMID 28184355, 2017).
developmental delay (1 paper, 2025). "Additionally, FBLN7 and TMEM87B, alone or in combination with other genes in the region, may also be involved in neurological features such as developmental delay - phenotypes that are more difficult to assess in zebrafish models." (PMID 40979016, 2025).
heart failure (1 paper, 2025). Inability of the heart to pump blood at an adequate rate to meet tissue metabolic requirements. "Given that age-related fibrosis is a significant pathological factor in heart failure with preserved ejection fraction (HFpEF), downregulating FBLN7 and/or interfering with its function may represent an effective therapeutic strategy for HFpEF." (PMID 40860136, 2025).
Hypertension (1 paper, 2024). The presence of chronic increased pressure in the systemic arterial system. "In conclusion, these results clearly indicate that FBLN7 involved in the pathogenesis of hypertension-induced vascular remodeling." (PMID 39659565, 2024).
hypertrophic cardiomyopathy (1 paper, 2023). A condition in which the myocardium is hypertrophied without an obvious cause. "Microarray dataset analysis reveal FBLN7 is upregulated in human heart samples from patients with dilated and hypertrophic cardiomyopathy compared with non‐failing hearts." (PMID 37344348, 2023).
Inguinal hernia (1 paper, 2025). Protrusion of the contents of the abdominal cavity through the inguinal canal. "In our study, the direct induction of both FBLN7 and FBLN3 by E2/ESR1 amplifies the potential applicability of these findings across a broad spectrum of inguinal hernias." (PMID 39903526, 2025).
open-angle glaucoma (1 paper, 2020). Chronic outflow obstruction of the eye's drainage canals that can lead to increased internal eye pressure and optic nerve damage. "The study showed that Fbln7 expression in hAH of primary angle-closure glaucoma (PACG) patients is significantly lower as compared to non-glaucomatous controls and primary open-angle glaucoma (POAG) patients." (PMID 32429873, 2020).
osteoarthritis (1 paper, 2025). A noninflammatory degenerative joint disease occurring chiefly in older persons, characterized by degeneration of the articular cartilage, hypertrophy of bone at the margins and changes in the synovial membrane. "Given the potential role of the FBLN7-TGFBR3 interaction in other age-related diseases, such as tumors and osteoarthritis, these mechanisms warrant further investigation." (PMID 40860136, 2025).
renal fibrosis (1 paper, 2025). A final common manifestation of a wide variety of chronic kidney diseases characterized by glomerulosclerosis and tubulointerstitial fibrosis. "To eliminate the potential indirect effects of blood pressure, body weight, metabolism, cardiac vessel density, and vascular and renal fibrosis on cardiac fibrosis, we examined the impact of FBLN7 overexpression in FSP1+ cells on these variables." (PMID 40860136, 2025).
retinal disease (1 paper, 2017). "Three genes had SNP associations to retinal disease: Ldlrad3, Fads2, and Fbln7." (PMID 29116131, 2017).
cancer (3 papers, 2018 to 2021). A tumor composed of atypical neoplastic, often pleomorphic cells that invade other tissues. "Due to the fact that Fbln7 is expressed in endothelial cells and its C terminal fragment inhibits blood vessel formation, it is conceivable that Fbln7 may be associated with cancer pathogenesis." (PMID 32429873, 2020). "Although not statistically significant, there was a trend toward downregulation of FBLN2 and FBLN7 in cancer tissue relative to benign." (PMID 29581841, 2018). "An in-depth study is required to explore the involvement of fibulin-7 in cancer." (PMID 34063320, 2021). "Thus, administration of Fbln7-C or endogenously expressed Fbln7 in the endothelial cells may be beneficial in modifying the functions of cancer and immune cells such as TAM and regulate cancer pathogenesis." (PMID 32429873, 2020).
FBLN7 also shares sentences with these, for which no sentence is quoted: breast tumors (2 papers); aortic stenosis (1); astrocytic tumor (1); autoimmune disease (1); breast carcinoma (1); Cluster headache (1); fungal infections (1); glioma (1); hypertensive heart disease (1); hypertrophy (1); Macular dystrophy (1); myocardial infarction (1); Obesity (1); ovarian carcinoma (1); primary angle-closure glaucoma (1); retinopathy (1); retinoschisis (1); rheumatoid arthritis (1); Sepsis (1); systemic lupus erythematosus (1); triple-negative breast carcinoma (1); tumor (1).